OGG1 (8-oxoguanine DNA glycosylase)
Diseases named in the same sentence as OGG1 in open-access papers (continued):
Sharing a sentence is not in itself a finding about the gene and the disease.
cancer (continued). "We found that the OGG1 Cys326 variant, which affected 37% of the 287 patients in the sample, was strongly linked with a worse outcome, in particular cancer-specific survival." (PMID 34199885, 2021). "Of interest, in comparison to Ogg1−/− mice, Ogg1−/−Mutyh−/− mice were further predisposed to develop cancer, presenting with predominantly lung and ovarian tumors, and B-cell lymphomas." (PMID 32547565, 2020). "It has been shown that a polymorphic variant of OGG1 (serine to cysteine amino acid substitution at position 326) is associated with a higher risk of developing several types of cancer." (PMID 32850458, 2020). "The fact that EC aerosols used in this study, like MS smoke, can lead to a significant decrease in the expression of ERCC1 and OGG1, suggest yet another mechanism by which exposure to EC aerosol can contribute to DNA damage, and therefore increase cancer risk." (PMID 28542301, 2017). "By its fundamental role in the system BER, mutation and polymorphisms in the gene OGG1 are considered events that increase the susceptibility to various forms of cancer." (PMID 29257843, 2017). "Studies based on a mouse model with OGG1−/− knock-out revealed this deficiency to have minor or even marginal importance in pathogenesis and cancer frequency." (PMID 26649135, 2016). "A meta-analysis to assess the role of OGG1 Ser326Cys polymorphism in the cancers of the upper aero-digestive and gastrointestinal tract was therefore undertaken in order to resolve this ambiguity." (PMID 27026921, 2016). "Several studies report that the OGG1 Ser326Cys polymorphism increases the risk for cancers of the upper aero-digestive and gastrointestinal tract." (PMID 27026921, 2016). "Previous studies including several meta-analyses pertaining to the role of OGG1 Ser326Cys polymorphism with the risk for different cancers were found to be ambiguous." (PMID 27026921, 2016). "Subgroup analysis based on cancer types and ethnicity also revealed the association of OGG1 Ser326Cys polymorphism to the risk for upper aero-digestive and gastrointestinal tract cancers among both the Asian and the Caucasian populations." (PMID 27026921, 2016). "We have previously found that the OGG1 SNP rs2304277may be a modifier of cancer risk in BRCA1 mutation carriers." (PMID 27015555, 2016). "Stratified analysis based on ethnicity reveals that the OGG1 polymorphism increases the risk for cancer in both Asian and Caucasian populations." (PMID 27026921, 2016). "Based on our search criteria, 152 studies relevant to the role of OGG1 mutations/polymorphisms on cancer/disease susceptibility were identified." (PMID 26089588, 2015). "Results of current meta-analysis revealed that 60 out of 62 selected studies focused only on OGG1 mutation (Ser326Cys) for its role in carcinogenesis and the majority of studies (60%) concluded association of this mutation with different cancers." (PMID 26089588, 2015). "Findings of all previous studies investigated for this meta-analysis were contradictory regarding association of OGG1 polymorphisms to increased risk of cancer susceptibility." (PMID 26089588, 2015). "BRCA2 N372H (rs144848), XRCC1 R399Q (rs25487), and OGG1 S326C (rs1052133) are three SNPs in DNA repair genes consistently associated with cancer risk, supported by thirty studies." (PMID 18547414, 2008). "The OGG1 Ser326Cys polymorphism may be a risk factor for cancers of the lungs, digestive system, and head and neck." (PMID 36620083, 2022). "Data from the Cancer Genome Atlas on OGG1 indicate that a number of single nucleotide polymorphisms found in patients with cancer result in mutations into cysteine (for example, R97C and R330C), which may further sensitize the protein to oxidation." (PMID 33203705, 2021). "This may in part explain why Ogg1 knockout mice are largely spared from cancer, and the relative rarity of the expected C→A mutation signature in human cancers in spite of the well-demonstrated fundamental role of ROS in hyperplasias." (PMID 33211885, 2020).
cancer (continued). "Furthermore, a well-characterized single nucleotide polymorphism of OGG1 (serine 326 to cysteine) exists that lacks efficient repair of 8-oxoguanine and is associated with a higher risk of cancer development." (PMID 33282879, 2020). "Additionally, a well-characterized single nucleotide polymorphism of OGG1 (serine 326 to cysteine) is associated with a higher risk of developing a number of different cancers, due to deficiencies in the repair of 8-oxoguanine." (PMID 33282879, 2020). "Among the established polymorphisms of the DNA repair genes, the X-ray cross-complementing group 1 (XRCC1) and 8 Oxo guanine DNA-glycosylase 1 (OGG1) polymorphisms have been frequently studied as potentially related with susceptibility to the incidence of several cancers." (PMID 32711416, 2020). "We tried to explain this cancer association at a molecular level and we discovered that the SNP was associated with a constitutive OGG1 transcriptional down-regulation, which contributed to a higher genome and telomere instability, especially in those individuals harboring mutations in BRCA1." (PMID 29383107, 2017). "Although the relationship between hOGG1 expression and cancer risk and the Ser326Cys hOGG1 polymorphism and the expression of OGG1 has been reported, the results of previous genetic studies on the relationship between hOGG1 polymorphism and various cancers risks were conflicting and contradictory." (PMID 28415770, 2017). "Furthermore we have stratified the studies based on ethnicity to determine the role of OGG1 Ser326Cys polymorphism in the risk for cancer among different ethnic groups." (PMID 27026921, 2016). "Our study reveals an association between OGG1 Ser326Cys polymorphism and cancer susceptibility of the upper aero-digestive and gastrointestinal tract (CG + GG vs CC; odds ratio, OR 1.22; 95 % CI 1.05–1.41; GG vs CG + CC; OR 1.36; 95 % CI 1.09–1.70; GG vs CC; OR 1.46; 95 % CI 1.12–1.92)." (PMID 27026921, 2016). "OGG1 gene is highly polymorphic among humans and is also mutated in cancer cells." (PMID 26089588, 2015). "Previous study show that mutations in OGG1 are associated with cancer and the efficacy of DNA repair may determine the susceptibility to carcinogens." (PMID 24797175, 2014). "This suggests that OGG1 326 Ser/Cys polymorphism may be a risk factor for developing some cancer types." (PMID 25526641, 2014). "Among the other 5 OGG1 variants, c.−18G>T and c.977C>G (p.Ser326Cys) have been reported as low-penetrance cancer susceptibility variants, while the remaining three were untranslated, synonymous, or intronic variations, meaning that all of them are not highly pathogenic mutations." (PMID 24799981, 2014). "Previous studies demonstrated that genetic variation in OGG1 affects cancer susceptibility; the frequency of the OGG1 326Cys allele was found to be significantly higher in patients when compared with controls; however, this association was not replicated by other studies." (PMID 22540013, 2012). "Also, significant association has been observed between OGG1 Ser326Cys polymorphism and risk of esophageal, lung, bladder, breast and colon cancers." (PMID 21283657, 2011). "The OGG1 gene is somatically mutated in some cancer cells and is highly polymorphic among humans." (PMID 19265534, 2009). "Dysregulation of human DNA repair gene OGG1 is associated with an increased cancer risk." (PMID 19265534, 2009). "In addition, OGG1 plays a crucial role in effective DNA damage repair and is encoded by a gene at 3p26.2, a region in the human chromosome, commonly associated with loss of heterozygosity in various human cancers." (PMID 37627097, 2023). "Importantly, we show that multiple cancer cell lines are sensitive to loss or inhibition of OGG1, which could relate to an underlying addiction to a functional OGG1 in cancer." (PMID 33211885, 2020).
cancer (continued). "Although many polymorphisms have been reported in OGG1, the C/G polymorphism at the 326 codon of exon 7 which results in an amino acid substitution from serine to cysteine is of great importance as it has been linked to the increased risk for different cancers." (PMID 27026921, 2016). "Moreover studies involving relatively larger population for exploration of different OGG1 mutations (novel as well as reported) in relation to other clinicohistopathological parameters may also be needed for their role in cancer development." (PMID 26089588, 2015). "OGG1 removes 8-oxodeoxyguanosine which is generated by oxidative stress and is highly mutagenic, and it has been suggested that SNPs in the gene could be associated with cancer risk." (PMID 24698998, 2014). "However, given the abundance of 8-oxoguanine and the suspected role of oxidative stress in cancer, reduced OGG1 activity might be associated with the risk of some other cancers as well." (PMID 20718982, 2010). "Reduced OGG1 activity could be expected to be a risk factor in other smoking-related cancers." (PMID 20718982, 2010). "Recent studies demonstrate that inhibition of OGG1 is a promising strategy for the development of drugs against cancer and inflammation." (PMID 39966348, 2025). "Numerous studies have demonstrated that OGG1 plays a pivotal role in inflammation, cancer, and age-related diseases." (PMID 40867876, 2025). "According to the current research, OGG1’s ability to facilitate the binding of NFκB and Myc to their respective DNA motifs can change cancer progression and make cancer cells resistant to chemotherapy and radiation." (PMID 39851540, 2025). "Under such conditions, expression of genes such as OGG1 or MTH1 is increased to shield cancer cells from excessive DNA damage." (PMID 39741341, 2025). "Conversely, clinical observations have revealed a complex relationship between OGG1 expression and cancer development, which seemingly contradicts the mutagenic potential of 8-oxoGua." (PMID 39741341, 2025). "The anti-inflammatory and anti-cancer effects of the OGG1 inhibitors were evaluated in disease-relevant cell models." (PMID 39966348, 2025). "We computationally dock a set of 14 million fragments to 8-oxoguanine DNA glycosylase (OGG1), a difficult drug target involved in cancer and inflammation, and evaluate 29 highly ranked compounds experimentally." (PMID 39966348, 2025). "Enzymes such as OGG1 are integral to the pathways that regulate cancer and inflammation, making them promising targets for diagnosis and future therapeutic interventions." (PMID 40813502, 2025). "In OGG1-deficient cells, CHD4 was unable to bind to the tumor suppressor gene promoter, despite 8-oxoGua accumulation, suggesting an upstream role for OGG1 prior to CHD4 in cancer initiation." (PMID 39741341, 2025). "We also characterized 37 cancer-derived SIRT2 mutants and found that 5 exhibited the loss of the stimulatory effects on OGG1 transcription." (PMID 38554113, 2024). "OGG1 is an important player in gene expression, cancer, inflammation, neurodegenerative diseases, and many pathological conditions." (PMID 39341999, 2024). "The pharmacological targeting of oxidative BER proteins in cancer therapies has resulted in the identification of OGG1 as an anti-tumor cancer target." (PMID 36768357, 2023). "OGG1 inhibitors are therefore proposed as potential promising therapeutical tools for the treatment of cancer." (PMID 36819096, 2023). "In a study of broader scope, the OGG1 enzymatic activity was examined as a target for cancer cell killing due to the proven dependence of several cancer cell types on PARP and BER." (PMID 38201575, 2023). "We also found that OGG1 expression in adipose tissue was lower in late-stage cancer when compared with patients with early-stage cancer (p = 0.028)." (PMID 36982562, 2023).
cancer (continued). "In the present work, we identified two out of three tested cancer associated ABC transporters, ABCB1/MDR1 and ABCG2/BCRP, as off-targets of the OGG1 inhibitors TH5487 and SU0268." (PMID 36819096, 2023). "The association between cancer and several other mitochondrial-related proteins, such as silent information regulator 3 (SIRT3), mitochondrial tumor suppressor gene 1 (MTUS1), and 8-hydroxyguanine DNA glycosylase (OGG1), has been reported." (PMID 37627097, 2023). "Accordingly, we found that OGG1 was upregulated in adipose tissue from patients with CRC in comparison with normal participants, indicating increased OGG1 activity to mitigate the high levels of 8-oxo-2′-deoxyguanosine observed in the cancer context." (PMID 36982562, 2023). "In order to evaluate if the effects observed for OGG1 inhibitors were indeed dependent on the levels of expression of the efflux pumps we selected different cancer cell lines according to their respective expression levels of BCRP and MDR1." (PMID 36819096, 2023). "Taken together, facilitation by OGG1 of NFκB and Myc binding to their cognate motifs on DNA can alter the course of malignancy and render cancer cells resistant to chemo/radiotherapy." (PMID 38201575, 2023). "Repairing of mutagenic base byproducts by OGG1 is essential to maintain the integrity of the genome and to prevent cancer development." (PMID 36178927, 2022). "OGG1 binds to oncosuppressor gene promoters and recruits chromodomain helicase-DNA-binding protein 4 (CHD4), which is associated with cancer." (PMID 36620083, 2022). "Their results showed that MTH1 depletion in cancer cells resulted in the accumulation of 8-oxoG in DNA, and the addition of OGG1 increased DNA strand breaks, while temporarily inhibiting the survival and viability of tumor cells." (PMID 36497058, 2022). "Both OGG1 genetic depletion and pharmacological inhibition have provided evidence for a crucial OGG1 role in protecting telomeres from the harmful effects of high oxidative stress in cancer cells." (PMID 34869348, 2021). "Pre-incubation with OGG1 significantly increased the number of DNA breaks revealed by alkaline comet assay in the cancer cells, indicating the presence of a large number of 8-oxoGua in the cancer DNA." (PMID 34425836, 2021). "In the present study, we characterize temporal-space OGG1 DNA repair activity at telomeres of cancer cells during basal and OS conditions." (PMID 33568707, 2021). "A recent study impaired BER with OGG1 inhibitor TH5487 in cancer cells under oxidative stress, and showed reduced XRCC1 recruitment and increased 8-oxoG levels in telomeric DNA." (PMID 34869348, 2021). "In this study, different approaches of CAAD are utilized to identify inhibitory molecules against the OGG1 enzyme, which is a potential target for treating cancer." (PMID 34948899, 2021). "From the biological standpoint, the “hyperactive” OGG1 mutants we observed are perhaps even more interesting than the inactivating mutants because of their somatic cancer origin." (PMID 33361155, 2021). "Our findings demonstrate that OGG1 is required to protect telomeres from OS and present OGG1 inhibitors as a tool to induce oxidative DNA damage at telomeres, with the potential for developing new combination therapies for cancer treatment." (PMID 33568707, 2021). "Although OGG1 depletion is well tolerated in non-transformed cells, we report here that OGG1 depletion obstructs A3 T-cell lymphoblastic acute leukemia growth in vitro and in vivo, validating OGG1 as a potential anti-cancer target." (PMID 33211885, 2020). "The effect of these OGG1 inhibitors in cellular and animal cancer models is currently being pursued." (PMID 32648895, 2020). "Here, we validate OGG1 as an anti-cancer target, which confirms targeting oxidative DNA repair as a concept for treatment of cancer." (PMID 33211885, 2020).
cancer (continued). "To further investigate if OGG1 depletion inhibited growth in human transformed and cancer cell lines we tested the colony forming ability in previously validated OGG1 CRISPR-Cas9 depleted epithelial kidney embryonic cells (HEK293T(KO))." (PMID 33211885, 2020). "Polymorphisms of MLH1, APEX1, MUTYH, OGG1, NUDT1, and XRCC5 are associated with sporadic CRC and other site‐specific cancers." (PMID 29664240, 2018). "In contrast, in cancer cells that have adapted to higher level of oxidative DNA damage by increasing BER gene expression, OGG1 can confer protection against damage caused by radiation, as observed in DLD-1 cells." (PMID 28147323, 2017). "Recent studies suggest that patients with CRC have lower expression of genes OGG1 and mutyh in tissue cancer when compared to normal tissues suggesting that these systems operate without a disability." (PMID 29257843, 2017). "In particular, two Single Nucleotide Polymorphisms (SNPs) in the OGG1 and NEIL2 genes were identified as cancer risk modifiers for BRCA1 and BRCA2 mutation carriers, respectively." (PMID 29383107, 2017). "Treatment with each of the three OGG1 siRNAs reduced clonogenic efficiency of DLD-1 cancer cells following radiation." (PMID 28147323, 2017). "Alteration in the levels of OGG1 and polymorphisms in the OGG1 gene modulate BER capacity and are known risk factors for human cancer." (PMID 28542301, 2017). "To answer this question, we first tested the effect of OGG1 overexpression and observed that OGG1 increases the survival of DLD-1 cancer cells following radiation." (PMID 28147323, 2017). "While we know nothing of the pharmacokinetic properties of these compounds and cannot exclude the possibility of additional targets, these results are consistent with the notion that reducing OGG1 activity sensitizes cancer cells to radiation." (PMID 28147323, 2017). "We propose that the opposite effect of OGG1 overexpression in different cell lines is due to the fact that some cancer cells adapt to high levels of reactive oxygen species by enhancing BER activity." (PMID 28147323, 2017). "The OGG1 gene is frequently methylated in different cancers, and silencing of its expression by promoter region methylation is associated with poor prognosis in breast cancer." (PMID 26967246, 2016). "The rate of developing malignant tumors in Ogg1-KO mice was also significantly higher than in wild-type mice." (PMID 25029543, 2014). "The other three markers were decreased in the cancer patients by 16–29%: OGG1, Maspin and phospho-Src (P⩽0.01)." (PMID 19789535, 2009). "Three of these SNPs (CDKN1A-S31R, OGG1-S326C, and XRCC3-T241M) have already found to be associated with altered cancer risk." (PMID 16111488, 2005). "A further exploration of OGG1’s regulatory mechanisms and its role across different tumor types could provide new insights and potential strategies for cancer prevention and treatment." (PMID 40227353, 2025). "Therefore, targeting OGG1 for cancer therapy in obstetric and gynecologic malignancies warrants further in-depth investigation." (PMID 40813502, 2025). "Moreover, a previous study demonstrated that Ogg1 and Mutyh-dependent gene expression changes in a cancer cell line showed the highest enrichment in PRC2 target genes." (PMID 40779073, 2025). "Crystal structures of OGG1-fragment complexes combined with docking of tailored chemical libraries enable rapid discovery of potent inhibitors displaying efficacy in cell models of cancer and inflammation." (PMID 39966348, 2025). "Consequently, OGG1 is regarded as a viable therapeutic target for the treatment of inflammation, cancer, and age-related diseases." (PMID 40867876, 2025). "OGG1 knockdown and treatment of cells with OGG1 inhibitors sensitize cancer cells to radiation." (PMID 38287022, 2024).